IL6R (interleukin 6 receptor)
Diseases named in the same sentence as IL6R in open-access papers (continued):
Sharing a sentence is not in itself a finding about the gene and the disease.
atherosclerosis (24 papers, 2011 to 2026). A disease characterized by the build-up of fatty material and calcium deposition in the arterial wall resulting in partial or complete occlusion of the arterial lumen. "Blockade of IL-6R and IL-6 signaling reduces atherosclerosis in mice when Tet2 is deficient by reducing expression of Csf1r." (PMID 40874164, 2025). "Interleukin-6 (IL-6) as a cytokine plays an important role in the “response to injury” model of endothelial cells and atherosclerosis, and it is encoded and regulated by the IL-6 receptor (IL6R) gene, which is located in the chromosome 1q21." (PMID 38827573, 2024). "It is IL-6R ‘trans-signalling’, where IL-6 binds to soluble forms of IL6-Rα (sIL6-Rα) and triggering hyperactivation of gp130, that is thought to underlie the pro-inflammatory actions of IL-6 in a variety of diseases, including atherosclerosis." (PMID 23782265, 2013). "Interestingly, IL-6R is also implicated in atherosclerosis mediated by clonal hematopoiesis." (PMID 40874164, 2025). "Among them, PCSK9 and IL6R are already being investigated as therapeutic targets for atherosclerosis." (PMID 40649979, 2025). "IL-2 and pSTAT5 are also potent inhibitors of Tfh differentiation, suggesting that cholesterol-mediated IL-2 signaling attenuation, together with increased IL-6R and Bcl6 expression, initiate Tfh differentiation in context of atherosclerosis." (PMID 29545616, 2018). "Five of them (ANGPTL4, APOB, BRAP, LPA, and ZPR1), were associated with increased levels of arteriosclerosis/atherosclerosis and risk of CVD, whereas four (DUSP13, FN1, IL6R, and MMP12) were associated with reduced levels of arteriosclerosis/atherosclerosis and risk of CVD." (PMID 42133815, 2026). "PCSK9 and IL6R are current therapeutic targets under investigation for atherosclerosis." (PMID 40649979, 2025). "Consequently, cholesterol-mediated attenuation of IL-2 signaling, along with the increased IL-6R and Bcl6 expression, initiate Tfh differentiation in the context of atherosclerosis." (PMID 33465845, 2021). "In addition, the role of IL-6R inhibition in the development and progression of atherosclerosis cannot be deducted from our data." (PMID 27936014, 2016). "The AAT haplotype of the IL-6R gene (rs4845617 G/A, rs4845623 A/G, and rs2229238 C/T) may play an important role in the pathogenesis of dyslipidemia and atherosclerosis in girls." (PMID 21835044, 2011). "The AAT haplotype of IL-6R gene SNPs rs4845617 G/A, rs4845623 A/G, and rs2229238 C/T may play an important role in the pathogenesis of dyslipidemia and atherosclerosis in girls." (PMID 21835044, 2011). "Despite the extensive evidence that inflammation is a key component of atherosclerosis, there has not been a large GWAS signal in loci harboring pro-inflammatory cytokines or chemokines, IL6R and CXCL12 loci being notable exceptions." (PMID 36792607, 2023).
diabetes (24 papers, 2012 to 2025). "Thus, to further assess the effects of diabetes on IL-6R-associated transcriptional activation, SOCS3 expression in the skin was assessed." (PMID 31073533, 2019). "Therefore, it is possible that IL-6R inhibition may yield clinically meaningful changes in glycaemia in people with inflammatory or immune conditions which are linked with diabetes." (PMID 33096487, 2020). "The same distribution was observed for IL-6R serum levels in subjects with diabetes (median 1511.75 ng/mL, range 416.75–1849.25 ng/mL) when compared with the non-diabetics (median 1220.5 ng/mL, range 611.75–1886.75 ng/mL; p = 0.046)." (PMID 38921685, 2024). "IL6 and its receptor, IL6R, appear to directly connect diabetes to schizophrenia, with multiple connections bridging through the other highlighted processes including GABAergic neurons, oxidative stress, and neuronal plasticity." (PMID 38573526, 2024). "At first, we explored the expression of IL6 and IL6R in human pancreatic islets and other metabolic tissues, as well as their correlation with diabetes status, using publicly available datasets." (PMID 38667300, 2024). "IL-6 subsequently binds to its receptor (IL6R) on hepatocytes to enhance the production of thrombopoietin, thereby regulating platelet production and resulting in diabetes-induced thrombocytosis." (PMID 35330392, 2022). "This seems to indicate that the regulation of IL-6 and IL-6Rα by hyperglycemia/diabetes resides at the posttranscriptional level." (PMID 31073533, 2019). "Prospective randomised clinical trials are needed to evaluate the effects of IL-6R inhibition on glycaemic indices, insulin sensitivity and pancreatic β cell function in patients with comorbid RA and diabetes and determine the clinical relevance of differences in IL-6R, IL-1β and TNF inhibition." (PMID 32907617, 2020). "The exact mechanism of interplay between IL-6, STAT3, and SOCS3 at an organismal level during diabetes is likely complex; thus, it was of interest to determine if hyperglycemia itself might mediate altered IL-6R function in keratinocyte culture." (PMID 31073533, 2019). "It has been suggested that diabetes-related oxidative stress may induce vascular IL-6 expression and activate IL-6R and gp130, which in turn activates the JAK2/STAT3 signaling cascade." (PMID 22553973, 2012). "Overall, the anti-IL6R drugs appear not to reduce the risk of diabetes mellitus." (PMID 35747747, 2022). "Previous studies have reported that low lymphocyte count at baseline, diabetes, APACHE II score, use of interleukin-6 receptor antagonists, use of corticosteroids, and ICU length of stay were risk factors for the development of bacterial superinfections." (PMID 36936237, 2023). "In a study of IL-6R inhibitors (tocilizumab and sarilumab) from the FAERS database, there was a strong correlation with gastrointestinal issues, except for hypercholesterolemia, severe infections, diabetes, and nervous system disorders." (PMID 39767766, 2024). "In this study, we aim to shed more light on the role of IL6 in insulin secretion and glucose metabolism by exploring the expression patterns of IL6 and IL6R in human pancreatic islets from donors with/without diabetes and their correlation with HbA1c, BMI, age, and gender." (PMID 38667300, 2024). "In this study, our constructed recombinant anti-IL-6R fusion proteins (VHH-0031), by linking 2 single domain chains against the pro-inflammatory cytokine receptor (IL-6R) and human serum albumin (HSA) respectively, presents potent renoprotective effect in diabetes both in vivo and in vitro." (PMID 34054555, 2021).
schizophrenia (21 papers, 2012 to 2025). A major psychotic disorder characterized by abnormalities in the perception or expression of reality. "Some of these proteins such as Factor VII, vWF, CgA, AAT and IL-6r have also been found to be altered or predict development of schizophrenia in ultra-high risk or pre-onset individuals." (PMID 28974776, 2017). "In addition to this finding, we also demonstrated that another SNP, rs7553796 located within the IL-6r gene was associated with increasing levels of the IL-6r protein in blood in both the control and schizophrenia groups." (PMID 28974776, 2017). "Polymorphic variants of the IL1B, IL6, IL6R, IL10, IL17A, and TNFA genes have been associated with schizophrenia." (PMID 37510364, 2023). "Altered levels of the membrane and/or soluble isoforms of gp130 and IL6R have been reported in the serum, cerebral fluid, and/or brain of patients with Alzheimer disease, amyotrophic lateral sclerosis, multiple sclerosis, and schizophrenia and bipolar disorder." (PMID 33037528, 2021). "For instance, SNPs of genes encoding major proinflammatory and anti-inflammatory cytokines, including interleukins (IL) IL1-β, IL-6, IL-6R, IL-10, IL-17A, and tumor necrosis factor α (TNF-α), are related to schizophrenia." (PMID 40416497, 2025). "Age of onset negatively correlated with CD14, IL6R, IL1R1, SERPINA3, pan-GFAP and VIM mRNAs in schizophrenia and CD14, IL1B, SERPINA3, pan-GFAP and VIM mRNAs in bipolar disorder." (PMID 34911938, 2021). "Duration of illness positively correlated with IL6, IL6R and SERPINA3 mRNAs and negatively correlated with P2RY12 mRNA in schizophrenia." (PMID 34911938, 2021). "Therefore, we investigated inflammation in the SEZ by defining those with low and high levels of inflammation using cluster analysis of IL6, IL6R, IL1R1 and SERPINA3 gene expression in 32 controls, 32 schizophrenia and 29 bipolar disorder cases." (PMID 34911938, 2021). "A significant inverse relationship was found between CC16 and IL-6 and IL-6R in patients with schizophrenia, but not in normal volunteers, once again pointing to the role of inflammation in schizophrenia, as indicated by higher IL-6 and IL-6R serum level, which may be linked to lower serum CC16." (PMID 30374300, 2018). "IL-6 and IL-6R were significantly higher in patients with schizophrenia than in normal controls and IL-6 was significantly higher in TRS than in normal controls, whereas patients with non-resistant schizophrenia TRS had intermediate values." (PMID 30374300, 2018).
type 2 diabetes (21 papers, 2011 to 2025). "The IL-6R gene is located on human chromosome 1q21, a region that previous studies have reported to be linked to metabolic syndrome, type 2 diabetes and atrial fibrillation." (PMID 24699044, 2014). "Our safety profiling of IL6R blockade in the genetic experiment included the effect of IL6R variants on established cardiovascular risk factors such as type 2 diabetes and blood pressure." (PMID 22421340, 2012). "The IL-6R gene is located on human chromosome 1q21, a region reported to be linked to dyslipidemia, metabolic syndrome, and type 2 diabetes." (PMID 21835044, 2011). "We identified 29 traits with differences in IL6R variant-phenotype associations, including a lower risk of type 2 diabetes in AFR (OR 0.96) vs EUR (OR 1.0, p-value for heterogeneity = 8.5 × 10–3), and higher white blood cell count (p-value for heterogeneity = 8.5 × 10–131)." (PMID 38580710, 2024). "In a meta-study examining 15 reports of 5421 total cases of type 2 diabetes, IL-6 was strongly related, a finding supported by a subsequent multi-ethnic analysis of 260,614 diabetics which found that Asp358Ala mutations in the IL-6 receptor (IL-6R) were correlated with type 2 diabetes." (PMID 36143948, 2022). "However, it is unclear whether there is a genetic association between variants in the IL-6 receptor gene (IL6R) and type 2 diabetes risk." (PMID 33096487, 2020). "We measured the abundance of the IL-6 receptor (IL-6Rα) in skeletal muscle biopsies and isolated satellite cells from healthy (He), obese (Ob) or obese persons with type 2 diabetes (DM)." (PMID 22761857, 2012). "We then investigated the IL-6Rα protein abundance in an in vitro model consisting of satellite cells isolated from healthy (He), obese (Ob) and people with type 2 diabetes (DM) and differentiated in vitro into myocytes." (PMID 22761857, 2012). "If so, then blocking IL-6 mediated inflammation via the IL6R may help prevent or treat type 2 diabetes." (PMID 33096487, 2020). "Interestingly, the anti-inflammatory drug Metformin (1,1-dimethylbiguanide hydrochloride), a frequently used drug to treat type 2 diabetes, showed similar effects to the IL-6R antibody." (PMID 23372803, 2013). "Among subjects at higher risk of type 2 diabetes, an acute postprandial intervention of MUFA breakfast (72 E%) containing macadamia nut oil showed that several inflammatory genes were upregulated in subcutaneous adipose tissue (MCP-1, IL-1β, IL-6, IL-6R, TNF-α and TNFRSF1A)." (PMID 28076613, 2017). "By utilizing western blot analysis, we demonstrate that IL-6Rα protein was down regulated in skeletal muscle biopsies from obese persons with and without type 2 diabetes." (PMID 22761857, 2012). "Interestingly, serum levels of IL-6 (r=0.21, p<0.05), sIL-6R (r=0.31, p<0.01) and sgp130 (p=0.35, r<0.01) were positively correlated with age, a correlation that we had previously not observed for these proteins in type 2 diabetes patients." (PMID 39835136, 2024).
Autoimmunity (20 papers, 2012 to 2026). The occurrence of an immune reaction against the organism's own cells or tissues. "This IL-6 cluster signaling has been reported to be crucial for the development of pathogenic Th17 cells, and depletion of IL-6 or IL-6R only on DCs protected mice in an experimental autoimmune mouse model." (PMID 38469154, 2023). "IL-6R was associated with autoimmunity based on the considerable expression in tissue sections, which was also verified by the alleviated symptoms after blocking IL-6R expression." (PMID 25097512, 2014). "Moreover, increased circulating Treg levels and clinical benefits were observed in patients receiving IL-6R blockade by tocilizumab for management of autoimmune disorders at risk or during manifestation of autoimmunity-mediated renal disease." (PMID 39723211, 2024). "Subtle differences in the phenotype of the CD4+ T cells, specifically TEM cells, highlight IL-6-regulated pathways of interest, including the apoptotic pathway that may contribute to observed association of this IL6R SNP for development of autoimmunity." (PMID 35911690, 2022). "While, IL-6 trans-signalling and trans-presentation may be a more potent inducer of autoimmunity than classic signalling, our finding that blood IL6R and IL6ST expression are associated with increased risk of type 1 diabetes may be explained by any of the three signalling modalities." (PMID 39271518, 2024). "The monoclonal antibody tocilizumab targets the IL-6 receptor (IL-6R) and is used to treat various autoimmune conditions, including giant cell arteritis, cytokine release SJIA, and RA." (PMID 38605952, 2024). "Disruption of the IL-6/IL-6R interaction upstream of STAT3 via the anti-IL-6R monoclonal antibody tocilizumab was shown to partially improve autoimmunity by increasing FoxP3 + Treg cells." (PMID 37702894, 2023). "Overall, these results emphasize the significance of HuR in regulating the IL-6/IL-6R signaling axis in T cell activation and disease, which is in line with our recent work that HuR plays an important role in autoimmune neuroinflammation." (PMID 34395636, 2021). "An inhibitory mAb, Tocilizumab that binds human IL-6R and blocks its binding to IL-6 has been developed and is currently approved for the treatment of autoimmune conditions." (PMID 31491838, 2019). "Soluble interleukin-6 receptor (sIL-6R) levels positively correlate with disease progression in some autoimmune conditions and psychiatric disorders." (PMID 22911828, 2012). "Better understanding of IL-6 signaling pathways downstream of IL-6R may lead to the development of more targeted therapies to modulate inflammation and autoimmunity." (PMID 40936905, 2025). "In this signaling mode, the complex of IL-6 and membrane-bound IL-6R on dendritic cells is presented to gp130-expressing T cells; a process which seems to be required for priming of pathogenic TH17 cells, a subset of T cells implicated in autoimmunity and chronic inflammation." (PMID 41543641, 2026). "Despite these encouraging results, efforts to apply IL-6 or IL-6R blockade prospectively with therapeutic intent in clinical trials have lagged behind preclinical data, possibly due to resistance to repurpose these drugs from autoimmunity into the oncology setting." (PMID 36881480, 2023). "Satralizumab, a monoclonal antibody targeting IL-6R, is utilized in the treating of neuromyelitis optica spectrum disorder (NMOSD), a rare autoimmune disorder that primarily affecting the spinal cord and optic nerves." (PMID 38605952, 2024). "In summary, it is shown that a targeting of MST1 in DCs promotes IL-6 along with the expression of IL-6Rα/β and STAT3, thereby contributing to the programming Th17 cell differentiation in the inflammation that arises in both autoimmunity and fungal infection." (PMID 28145433, 2017).
Autoimmunity (continued). "The pathophysiology of autoimmunity however, is complex, explaining the observations that certain therapeutic strategies are effective in some AIDs (e.g., IL-6R blockade in RA), while exhibiting no benefit in others (e.g., IL-6R blockade in AS)." (PMID 28098832, 2017). "We provide evidence that a small subset of CD4+IL-6R+ TEM cells from carriers of the “non-risk/CC’ genotype show higher sensitivity to FAS agonist-induced expression of early apoptotic markers (Annexin V+ cells), potentially leading to decreased survival of pathogenic T cells in autoimmunity." (PMID 35911690, 2022).
Insulin resistance (20 papers, 2015 to 2025). Increased resistance towards insulin, that is, diminished effectiveness of insulin in reducing blood glucose levels. "Conversely, T cell-specific or natural killer cell-specific IL-6R deficiency ameliorated insulin resistance in obese mice, indicating that IL-6 can exert both pro-inflammatory and anti-inflammatory actions." (PMID 38321233, 2024). "There we observed that hepatic IL-6Rα deficiency results in exacerbated systemic inflammation originating from liver-resident Kupffer cells to result in the development of insulin resistance that also affect expression of glycolytic and glycogenic enzymes." (PMID 30224299, 2018). "Moreover, enhanced inflammation in liver and skeletal muscles and insulin resistance was observed in hepatocyte-specific IL-6R deficient animals, as well as increased insulin resistance in whole-body IL-6 KO mice and increased body weight in astrocyte-specific IL-6 deficient mice." (PMID 36387898, 2022). "In humans, ADAM17 expression and enzymatic activity were increased in T2DM skeletal muscle, as were the substrates TNF-α and IL6-R, which positively correlated with insulin resistance." (PMID 38963109, 2024). "Although IL-6 protects against obesity and insulin resistance, it can also be pro-inflammatory owing to its trans signaling, in which IL-6 binds soluble IL-6R and then forms a heterotrimer with gp130 expressed on the cell surface." (PMID 34576181, 2021). "Complementary to this, hepatocyte-specific IL6R, IL6, or STAT3 deficient mice develop increased gluconeogenesis and insulin resistance, as a result of G6pc upregulation, likely via a PI3K/FoxO1-independent pathway, as well as age-related obesity and steatosis." (PMID 30374109, 2018). "In addition, insulin resistance and glucose intolerance are observed in mice with liver-specific IL-6Rα KO, resulting in increased IL-6, IL-10, and TNF-α expression." (PMID 38999780, 2024). "Nonetheless, it is possible that IL-6 and IL-6 receptor (IL-6R) signaling in adipose tissue-resident macrophages may induce clinical inflammation and mediate insulin resistance." (PMID 34576181, 2021). "The increased concentration of soluble IL6R may be suggestive of metabolic syndrome and insulin resistance in T1D patients." (PMID 29445381, 2018).